APOE (apolipoprotein E)
Diseases named in the same sentence as APOE in open-access papers (continued):
Sharing a sentence is not in itself a finding about the gene and the disease.
amyloid (continued). "Recent work undertaken using specific antibodies to APOE suggests that APOE might compete with clearance mechanisms for Aβ at the BBB, and suggests potential novel targets for therapeutic intervention to reduce amyloidosis." (PMID 24587158, 2014). "Thus, if amyloid PET is capturing CAA-relevant amyloid in the A4/LEARN and ADNI samples, our analyses may not accurately capture the magnitude of amyloid-mediated effects of APOE on tau." (PMID 36597122, 2023). "Given that middle-aged and older APOE-ε4 carriers, on average, have more AD-related pathology than non-carriers due to an earlier onset of amyloid accumulation, these results suggest that individuals with higher levels of CR may be better able to tolerate early AD-related brain changes." (PMID 36978190, 2023). "However, whether decreasing levels of ApoE would attenuate amyloid pathology in different amyloidoses has not been directly addressed." (PMID 36436561, 2022). "This clearance route is likely deficient in APOE4 carriers, as shown by the co-localization of APOE and non-fibrillar Aβ in the perivascular space and neuropil surrounding cerebral arteries of human AD brains and also preclinical transgenic models of amyloidosis on the human APOE background." (PMID 34238312, 2021). "Additionally, global Bmal1 knockout abolished the rhythmic expression of soluble Aβ peptide in hippocampal interstitial fluid and increases amyloid plaque deposition in a mouse model of β-amyloidosis (APPPS1-21), which might be mediated by the increased expression of apolipoprotein E (Apoe)." (PMID 34595127, 2021). "Besides these, other proteins like ApoAIV, ApoE, APC, and vitronectin, the well-known components of the so called “universal amyloid proteome” in systemic amyloidosis, were all identified in our localized amyloidosis cases with much higher intensities than the former three." (PMID 31531279, 2019). "Additional “peaks”, primarily among the amyloid signature proteins APOA4, APOE and VTN have been reported before, but should not be misinterpreted as indicative of mixed amyloidosis." (PMID 40701201, 2025). "NLF and E4NLF mice showed incipient levels of Aβ plaques at 14–15 months with NLF mice exhibiting a non-significant trend toward increased amyloidosis compared with E4NLF mice, since E4 mice have no murine apoE expression." (PMID 41292846, 2025). "No SAP, ApoE or HSGPs were present in any of the deposits, even though SAP has been reported as present in all forms of amyloidosis." (PMID 40892784, 2025). "Finally, because we only examined Aβ+ individuals, we are unable to determine whether direct APOE effects on tau only emerge after amyloid positivity has been reached or whether the same direct APOE effects on tau would be present in the absence of amyloid." (PMID 36597122, 2023). "There is therefore a link between ApoE and Aβ that does not depend on their direct interaction but rather on the ability of the different isoforms of ApoE to modify the processing of APP through LRP8, thus representing a bidirectional bridge between cholesterol metabolism and amyloidosis." (PMID 36012187, 2022).
Stroke (321 papers, 2001 to 2026). Sudden impairment of blood flow to a part of the brain due to occlusion or rupture of an artery to the brain. "APOE variants affect lipid metabolism and cerebral amyloid angiopathy risk, altering stroke profiles in diabetic APOE4 carriers." (PMID 41567175, 2026). "Another study conducted in the same population found a similar positive association between ApoE levels and stroke risk." (PMID 41465167, 2025). "This association remained significant after adjusting for age, sex, education, race, ethnicity, APOE ε4 allele status, stroke, other vascular risk comorbidities, and WML volumes." (PMID 41249770, 2025). "A large-scale population-based study has shown that PSD incidence rates vary substantially with risk factors such as age, stroke severity, prior stroke, or APOE-ε4 genotype." (PMID 40893447, 2025). "A study found that small gold nano-particles accumulate in atherosclerotic plaque areas of ApoE knockout mice on a high-fat diet (instillation of the gold particles) and in surgical specimens of carotid artery disease from patients at risk of stroke." (PMID 40319735, 2025). "This exonic variant in APOE, linked to the APOE-Є4 allele, exhibited a compelling correlation, with each copy of the allele associated with a 1.29-year earlier stroke onset." (PMID 39286457, 2024). "An association of APOE rs429358 with stroke AAO has been reported previously, and this variant has also been associated with longevity and the age of parental death." (PMID 39286457, 2024). "APOE-rs429358 is associated with stroke AAO in both sexes combined, although the magnitude of association is stronger in women than in men (unequal variance t-test, p = 4.3 × 10−4)." (PMID 39286457, 2024). "Risk factors to consider include age, prior stroke and cerebral microhemorrhages, antithrombotic/anticoagulant use, apoE ε4 allele carrier status, and dose of the drug." (PMID 38312931, 2024). "Among the various SNPs analyzed, only the APOE genotypes showed a positive association with the minor C rs429358 allele, increasing the risk of aspiration pneumonia in young post-stroke dysphagia patients." (PMID 36005151, 2022). "Further large population-based studies exploring the influence of APOE alleles on the association between carotid artery measures and MI or stroke are warranted." (PMID 35332187, 2022). "Further studies exploring the interaction between APOE alleles and carotid artery measures on incident MI and stroke are warranted." (PMID 35332187, 2022). "The association between possession of the APOE ε4 or ε2 genotype and lobar CMBs has also been shown in a stroke population." (PMID 35912087, 2022). "ApoE ε2 was reported as a risk factor of cerebral infarction in Japanese populations, but the association between ApoE ε2 and stroke occurrence was only prominent in individuals aged 70 years old and older." (PMID 34276537, 2021). "Recently, a proof-of-concept underlying the ABCA1/ApoE/HDL pathway mediates myelination during stroke repair ABCA1 knocked down in stroke mice showed a significant decreased in myelinated axons and myelin sheath thickness." (PMID 34436325, 2021). "ApoE ε4 allele is referred to as a predisposing factor for cerebral infarction and increases the risk for different stroke subtypes (IS, intracerebral and subarachnoid hemorrhage)." (PMID 33833872, 2021). "We illustrate these approaches by re-analysing primary-care-linked UK Biobank data relating to CYP2C19 genetic variants, Clopidogrel use and stroke risk, and data relating to APOE genetic variants, statin use and Coronary Artery Disease." (PMID 34495953, 2021). "The only significant differences found indicated that higher rates of MCI were associated with APOE ε4 status at wave 3 (P<0.001) and wave 5 (P<0.05), and history of stroke at wave 3 (P<0.01) and wave 5 (P<0.05)." (PMID 33480611, 2021).
Stroke (continued). "We illustrate these approaches by re-analysing primary-care-linked UK Biobank data relating to CYP2C19 genetic variants, Clopidogrel use and stroke risk, and data relating to APOE genetic variants, statin use and Coronary Artery Disease (CAD)." (PMID 34495953, 2021). "Limitations: The present study is not an investigation of a stroke treatment; it is a proof-of-concept study that mainly focuses on mechanisms underlying the ABCA1/ApoE/HDL pathway in mediating myelination during stroke repair." (PMID 32575457, 2020). "ApoE knock-out mice were found to be more susceptible to acute myocardial reperfusion injury and stroke outcomes." (PMID 32499562, 2020). "Our group demonstrated that the T2238C variant of the atrial natriuretic peptide (ANP) gene, a nonmodifiable risk factor for cardiovascular diseases including stroke, modulates ApoE level through miR-199 in vitro." (PMID 31941075, 2020). "These relations remained significant for stroke and mortality after correcting for cardiovascular risk factors and APOE-ε2/ε4 carriership." (PMID 31866930, 2019). "Our data indicate that administration of ApoE2 minimizes the adverse effects of ABCA1 deficiency after stroke, at least partially by promoting cholesterol traffic/redistribution and GM/WM remodeling via increasing the ApoE/HDL/ApoER2 signaling pathway." (PMID 30373276, 2018). "APOE ε4 allele positivity was associated with higher expression of amyloid and tau pathology in the subiculum and entorhinal cortex of post-stroke cases (p < 0.05)." (PMID 29311794, 2017). "Further analysis of the post-stroke cohort suggested that the presence of the APOE ε4 allele was responsible for driving amyloid and tau accumulation in those who possessed the allele (which was present in 50%) of the PSND subjects." (PMID 29311794, 2017). "In older stroke patients with early cognitive impairment, the presence of an APOE ԑ4 allele was reported to be associated with greater progression of cognitive decline." (PMID 26806700, 2016). "In the same population setting, a related study with a focus on stroke also found an increase in ApoE level associated with an increased risk of stroke." (PMID 27755538, 2016). "The APOE ε4 allele, a well-studied example that contributes to a small extent to individual and population risks of traits such as stroke, heart disease and dementia, is found in virtually all populations, albeit at varying rates." (PMID 25962947, 2015). "Vascular risk factors and/or stroke history was significantly different by APOE ε4 status (p < 0.05), with ε4+ participants showing lower Modified Hachinski Total scores." (PMID 23554593, 2013). "Meta-analysis of three candidate genes: MTHFR, ACE and APOE in Asian population, revealed a significant association of stroke with the MTHFR 677C>T polymorphism and APOE epsilon 4 alleles, in contrast to ACE gene insertion/deletion polymorphism." (PMID 22555977, 2012). "Those with both stroke and the APOE ε4 allele were approximately 15 times more likely to be demented." (PMID 20576093, 2010). "In the second study, therelationships of APOE genotype, stroke, and vascular risk factors with cognitivechange were investigated in the Atherosclerosis Risk in Communities (ARIC)Study." (PMID 29213654, 2010). "ApoE-ε4 is also independently associated with increased vascular Aβ deposition in large-vessel CAA leading to strokes." (PMID 19468344, 2009). "While the results in samples of persons of European descent indicated a null effect of the APOE ɛ4 allele on stroke, the pooled OR from studies of Chinese people was substantially higher, and their CIs did not overlap." (PMID 17455988, 2007). "We investigated the association between apoE genotypes and stroke subtypes by a case-control study in Bangladesh for the first time among south Asian countries." (PMID 11434425, 2001).
Stroke (continued). "We studied the association of apoE genetic polymorphism with stroke subtype in a Bangladeshi hospital-based population, which is the first of its type in South Asian countries." (PMID 11434425, 2001). "This approach will allow exploration of the relationship between cognition and factors such as APOE status, inflammatory response, chronic inflammation, insomnia, obstructive sleep apnoea, physical activity, social interaction, hearing loss and stroke recurrence, among others." (PMID 40924766, 2025). "PSD risk was further related to APOE-ε4 homozygosity and recurrent stroke during follow-up." (PMID 40893447, 2025). "Low plasma ApoE, abnormal cIMT, and alcohol use were each independently associated with stroke." (PMID 41541874, 2025). "APOE ε4 allele distribution demonstrated the expected pattern associated with AD risk (p = 1.50 × 10−219), with controls showing the lowest frequency of ε4 carriers (24.7 %) compared to AD patients (49.2 % carriers) and AD + Stroke patients (47.0 % carriers)." (PMID 40670231, 2025). "In other words, the association we detected between APOE and stroke AAO may be due to a survival bias." (PMID 39286457, 2024). "A second possibility is that the association of this variant with stroke AAO is a more general consequence of the APOE risk allele at this locus being associated with a shortened lifespan in general, i.e., an age-related decrease in the frequency of the risk allele." (PMID 39286457, 2024). "In conclusion, we detected a robust association of the APOE locus with stroke AAO and provided simulations to suggest that this association may be unrelated to ischemic stroke per se but related to a general survival bias." (PMID 39286457, 2024). "First, APOE genotype may modify the already strong risk factor for vessel disease to influence stroke recovery." (PMID 36640294, 2023). "Likewise, diet modulated micro ribonucleic acid target site and hypermethylated APOE genes are associated with risk of stroke." (PMID 37168667, 2023). "Specifically, the study analyzed whether cognitive dysfunction was related to the presence of the apolipoprotein E (APOE) epsilon 4 (ε4) allele, associated with worse outcomes following stroke." (PMID 37497308, 2023). "The relation between polymorphism of the ApoE gene and stroke, however, remains uncertain." (PMID 33833872, 2021). "Others have pointed that during the first-month post-stroke, the Apolipoprotein E (ApoE) ε4 polymorphism may be associated with poor recovery." (PMID 34276537, 2021). "Compromised basal NO release together with an intact receptor-stimulated NO response was also seen earlier in organ baths of Fbn1C1039G/+ (Marfan model), apolipoprotein E-deficient isolated mouse aortic segments and arteries of stroke-prone spontaneously hypertensive rats." (PMID 34769044, 2021). "Linear mixed-effects regressions related cardiac output to trajectory for each longitudinal neuropsychological outcome, adjusting for age, sex, race/ethnicity, education, body surface area, Framingham Stroke Risk Profile score, apolipoprotein E (APOE) ε4 status and follow-up time." (PMID 33240156, 2020). "APOE*ε2, like APOE*ε4, is also a genetic risk factor for stroke." (PMID 33148290, 2020). "In WP 2, the aim is to increase knowledge concerning the pathogenesis of early and late-onset PCI by analysing brain imaging, APOE ε4 typing and blood markers, and to explore associations between neurodegenerative disease, underlying vascular disease, inflammation and stroke characteristics." (PMID 30477436, 2018). "We now provide the first data that apoC-III, along with apoC-II and apoE, associates significantly and independently with incident stroke and myocardial infarction on the basis of a direct comparison of apolipoprotein levels by MRM-MS, rather than immunoassays." (PMID 28209220, 2017).
Stroke (continued). "Our results support the hypothesis that ApoE alleles modify the inflammatory responses in the brain and the periphery, thus contributing to altered functional outcome following stroke." (PMID 23957944, 2013). "The APOE gene encoding ApoE protein is one of the most extensively studied genes, especially for AD susceptibility, but also for other disease risk such as cardiovascular mortality and stroke." (PMID 23894628, 2013). "Stroke and APOE ε4 were also associated with increased odds of AD." (PMID 20576093, 2010). "Due to the profound effects on the functional and structural properties of the protein, different isoforms of ApoE are associated with different diseases such as stroke, multiple sclerosis, Parkinson's disease, alcoholic cirrhosis of the liver and type 2 diabetes." (PMID 18823563, 2008). "Birth cohort by decade, education, Framingham Stroke Risk Profile score, plasma homocysteine concentrations (at the 20th Original cohort and the 6th Offspring examinations), apolipoprotein E genotype (ε4 +ve/-ve); data from sex-specific regressions were pooled." (PMID 17903297, 2007). "A quantitative analysis of OR of these genes shows that the effect sizes are broadly similar across the different ethnic groups apart from APOE, which has a null effect in persons of European descent but a significant association with stroke in the Chinese and Japanese groups." (PMID 17455988, 2007). "Odds ratio* (95% CI) of ApoE alleles in stroke subtypes categorised by age group." (PMID 11434425, 2001). "ApoE genotype and allele distribution in stroke subtypes and control group." (PMID 11434425, 2001). "Whereas, some studies have demonstrated an association between low ApoE plasma concentration with stroke, others have not or have even demonstrated an opposite association, with higher circulating concentration of ApoE associated with a higher risk of incident stroke." (PMID 41541874, 2025). "APOE ε4 carriers may need closer monitoring and much stronger control of risk factors of stroke." (PMID 36640294, 2023). "Also, compromised basal, unstimulated NO release together with an intact receptor-stimulated NO response has been observed before in aortic segments of Fbn1C1039G/+ (Marfan model) mice, apolipoprotein E–deficient mice, stroke-prone spontaneously hypertensive rats and warfarin-fed DBA/2J mice." (PMID 36316014, 2023). "Associations were independent of cerebrovascular burden, suggesting that they may relate to increased neurodegenerative pathology (given the known association between APOE genotype and AD) or vulnerability to injury (given the association of APOE genotype with stroke recovery and neuroplasticity)." (PMID 35566762, 2022). "Hence, we further explored whether the associations of CCA-IMT and carotid plaques with risk of incident MI and stroke were modified by APOE allele status." (PMID 35332187, 2022). "Apolipoprotein E polymorphism may affect the risk of post-stroke aspiration pneumonia." (PMID 36005151, 2022). "In contrast, two APOE ɛ4/ɛ4 participants had aspiration pneumonia during the follow-up period, which may support our results that APOE ɛ4 may act as a risk factor for aspiration pneumonia after stroke." (PMID 36005151, 2022). "As wild-type mouse ApoE is equivalent to human ApoE3, it is reasonably to speculate that human ApoE3 may share similar effects as mouse ApoE and human ApoE4 may increase stroke risk possibly by compromising the ApoE-mediated astrocyte–endothelial cell interaction." (PMID 32513932, 2020). "However, measured against this consideration is the knowledge that, although the study is the largest of its type, the power of the study is relatively modest for detecting interaction effects between APOE *E4 and low prevalence risk factors such as head injury, stroke and hazardous alcohol use." (PMID 18620605, 2008).